ZNF287 (zinc finger protein 287)
Description:
May be involved in transcriptional regulation.
Synonyms: ZKSCAN13; ZSCAN45
Tractability: PROTAC: ubiquitination databases record sites on it.
Gene: Protein-coding gene on chromosome 17 (16,546,954 to 16,569,218, reverse strand). Ensembl gene ENSG00000141040.
Subcellular location: Nucleus
Subcellular location (Human Protein Atlas): Golgi apparatus; Basal body
Pathways (Reactome):
Gene expression (Transcription): Generic Transcription Pathway
Gene Ontology:
Molecular function: DNA-binding transcription factor activity, RNA polymerase II-specific; RNA polymerase II cis-regulatory region sequence-specific DNA binding
Biological process: regulation of transcription by RNA polymerase II; regulation of DNA-templated transcription
Cellular component: nucleus
Genetic constraint (gnomAD): Loss-of-function variants: 25 observed, 66.27 expected, observed/expected ratio (o/e) 0.38, 90% interval 0.27 to 0.53. The upper end of that interval is the gene's LOEUF score, 0.53, which puts it in group 2 of 6, group 1 being the genes least tolerant of losing a copy. Missense variants: 583 observed, 890.47 expected, observed/expected ratio (o/e) 0.65, 90% interval 0.61 to 0.7. Synonymous variants: 277 observed, 305.21 expected, observed/expected ratio (o/e) 0.91, 90% interval 0.82 to 1.
Homologues: Orthologues: chimpanzee ZNF287 (99% identical), macaque ZNF287 (98% identical), rabbit ZNF287 (91% identical), dog ZNF287 (91% identical), pig ZNF287 (89% identical), guinea pig ZNF287 (87% identical), rat Zfp287 (86% identical), mouse Zfp287 (83% identical), Drosophila melanogaster CG15269 (20% identical). Paralogues in human: ZKSCAN7 (39% identical), ZNF34 (33% identical), ZNF527 (32% identical), ZNF852 (31% identical), ZNF214 (31% identical), ZNF17 (31% identical), ZNF530 (31% identical), ZNF416 (30% identical), ZNF285 (28% identical), ZNF572 (27% identical), ZNF333 (27% identical), ZNF233 (27% identical), and 38 more.
Diseases named in the same sentence as ZNF287 in open-access papers:
ZNF287 is named in the same sentence as 1 disease in open-access papers, as found by Europe PMC text mining. Sharing a sentence is not in itself a finding about the gene and the disease.
ZNF287 shares sentences with these, for which no sentence is quoted: tumours (1 paper).